PAK4 (p21 (RAC1) activated kinase 4)
Diseases named in the same sentence as PAK4 in open-access papers (continued):
Sharing a sentence is not in itself a finding about the gene and the disease.
breast cancer (continued). "To gain better understanding of the role of PAK4 in breast cancer, we performed RNA-Sequencing (RNA-Seq) of two human breast cancer cell lines, Hs 578T and BT-549, 72 h after transfection with PAK4-targeting siRNA." (PMID 31399573, 2019). "In fact, we recently crossed the here presented mouse model of MMTV-Cre driven conditional PAK4 gene depletion with the MMTV-PyMT breast cancer model and observed an increased mammary tumor latency upon PAK4 depletion." (PMID 31594963, 2019). "For the first time, we identified a role function of the nuclear PAK4 in promoting the breast-to-bone metastasis of ERα+ breast cancer via PAK4–ERα-LIFR axis." (PMID 30177834, 2019). "Of relevance, we observed a positive correlation between PAK4 expression and the breast cancer proliferation score." (PMID 31399573, 2019). "The PAK4 overexpression in breast cancer relative to normal breast tissues was confirmed in two independent breast cancer datasets." (PMID 31399573, 2019). "Consistently, PAK4 overexpression is correlated with poor patient outcome in breast cancer patients, and its overexpression in cancer cell lines was shown to increase cell survival, anchorage-independent growth, cell migration, and invasion." (PMID 31594963, 2019). "PAK4 protein levels displayed a similar trend within a panel of six human breast cancer cell lines, most exhibiting PAK4 overexpression as compared with two independent batches of primary, non-immortalized HMECs." (PMID 31399573, 2019). "Consistently, PAK4 overexpression in breast cancer cells inhibited RELB binding to DNA, while PAK4 depletion increased RELB DNA-binding." (PMID 31399573, 2019). "Here, the authors show that PAK4 overrides this senescence in breast cancer cells through phosphorylation of RELB, thereby inhibiting transcription of the senescence regulator C/EBPβ." (PMID 31399573, 2019). "Increased SA-β-gal activity and decreased cell proliferation, both typical senescence responses, were observed upon PAK4 knockdown in all breast cancer cell lines here tested." (PMID 31399573, 2019). "By confocal imaging, we found that PAK4 and ERα entered the nucleus in breast cancer cell lines upon E2 stimulation." (PMID 30177834, 2019). "In mice, MMTV-PAK4 overexpression promotes spontaneous mammary cancer, while PAK4 gene depletion delays MMTV-PyMT driven tumors." (PMID 31399573, 2019). "Taken together, the data suggest that PAK4 overexpression in a low metastatic potential ER+ breast cancer cells induced metastatic bone colonization in vivo." (PMID 30177834, 2019). "Accordingly, we found that breast cancer cells with a depleted PAK4 were less efficient in migrating across the membrane as compared with the control cells with functional PAK4." (PMID 30177834, 2019). "The p21-activated kinase 4 (PAK4) oncogene is amplified and/or overexpressed in a large variety of human cancers, including, breast cancer." (PMID 30177834, 2019). "Together, this indicates that PAK4 overexpression in breast cancer correlates with unfavorable disease outcome." (PMID 31399573, 2019). "A second PAK4-inhibitor, termed PF-3758309 has also demonstrated anti-neoplastic efficacy through decreasing cellular proliferation in breast cancer cells." (PMID 29983868, 2018). "For example, PAK4 expression is significantly increased in breast cancer and is positively correlated with tumor progression." (PMID 29440672, 2018). "PAK4 protein levels are high in breast cancer cells and breast tumors, and the gene is often amplified in basal like breast cancers, which are frequently triple negative." (PMID 28198380, 2017). "PAK4 inhibition is significant because of the important links that have been found between PAK4 and many types of cancer, including breast cancer." (PMID 28198380, 2017). "First, our in vitro and in vivo studies demonstrated that high level PAK4 expression induces breast cancer cell growth and promoted clone formation, cell migration and invasion, which is consistent with previous reports." (PMID 28407679, 2017).
breast cancer (continued). "Several breast cancer cell lines with high levels of PAK4 protein were plated in tissue culture cluster plates." (PMID 28198380, 2017). "In contrast to its role in carcinogenesis when overexpressed, PAK4 silencing using RNAi in the human breast cancer cell line MDA-MB-231 results in a dramatic reduction in cell proliferation and migration." (PMID 28198380, 2017). "In osteosarcoma and breast cancer cell lines, PAK4 inhibition led to defects in the cell polarization and suppressed β-catenin phosphorylation." (PMID 27845911, 2017). "As for MCF-7 breast cancer cells, the levels of Pak4 mRNA and protein increased after 3 days of E2 stimulation." (PMID 28978098, 2017). "We found that PAK4 activates PI3K/AKT signaling in the MDA-MB-231 breast cancer cell line, and identified a strong link between PAK4 induced invasive phenotype and PAK4 activated PI3K/AKT signaling." (PMID 28407679, 2017). "Our results demonstrate that high level of PAK4 expression is associated with larger tumor size, more lymph node involved and advanced stages of cancer, and correlated with poor DFS and OS in breast cancer patients." (PMID 28407679, 2017). "To further evaluate the prognostic value of PAK4 in breast cancer, we performed univariate and multivariate analysis on patient data." (PMID 28407679, 2017). "Several genes are thought to be behind the tumour suppressor activity associated to miR-199a/b in breast cancer, such as HER241, PAK4/MEK/ERK39, and SWI/SNF42." (PMID 29051564, 2017). "This is the first comprehensive study to reveal the oncogenic and prognostic roles of PAK4 in breast cancer cells and cancer patients." (PMID 28407679, 2017). "Previous report indicated that knockdown of PAK4 obviously prohibited breast cancer cell proliferation." (PMID 28706947, 2017). "We performed a series of functional assays to determine the effects of high level PAK4 on cell proliferation and invasion of breast cancer cells." (PMID 28407679, 2017). "We assessed the steady state level of PAK4 protein in several breast cancer cell lines by western blot analysis." (PMID 28198380, 2017). "Among the other available PAK4 inhibitors, we have found that compound 1742 can also block the growth of breast cancer cell lines in our system, however it was less effective than KPT-9274 (Rane and Minden, unpublished results)." (PMID 28198380, 2017). "Next, the rate of migration and invasion of breast cancer cells overexpressing PAK4 increased 3.5 fold and 2.88 fold, respectively, compared to control cells (p < 0.001)." (PMID 28407679, 2017). "In MDA-MB-231 breast cancer cells, elevated levels of PAK4 expression correlated with an elevated level of phosphorylated AKT and a more invasive phenotype." (PMID 27845911, 2017). "PAK4 expression in breast cancer is adjacent normal tissues, breast fibroma, and breast cancer metastasis tissues, and breast cancer increased gradually." (PMID 27297086, 2016). "The purpose of our study was to explore the expression of PAK4 and P54 in breast cancer and the correlation of these proteins with pathological stages of breast cancer." (PMID 27297086, 2016). "In our study, expression of PAK4 in breast cancer was much higher than that in breast fibroma and increased gradually as breast cancer progressed (advanced invasive > early invasive > noninvasive)." (PMID 27297086, 2016). "The correlation between high PAK4 expression and unfavorable endocrine treated breast cancer patient outcome is consistent with a potential role for PAK4 in tamoxifen resistance." (PMID 26554417, 2015). "Stable overexpression of PAK4 significantly decreased the tamoxifen sensitivity in human MCF-7 breast cancer cells." (PMID 26554417, 2015). "Taken together, PAK4 appears as an interesting target to explore for the restoration of tamoxifen sensitivity in breast cancer." (PMID 26554417, 2015).
breast cancer (continued). "Here, we found that PAK4 expression was consistently correlated to poor patient outcome in endocrine treated and tamoxifen-only treated breast cancer patients." (PMID 26554417, 2015). "Knockdown of Pak4 dramatically reduced proliferation and migration of breast cancer cells, but the most dramatic finding was that Pak4 knockdown largely restored normal acinar structure." (PMID 23732710, 2013). "Here we show that Pak4 is also required for oncogenic transformation of the human breast cancer cell line MDA-MB-231." (PMID 23732710, 2013). "The Pak4 protein kinase, normally expressed at low level in the mammary gland, is commonly overexpressed in breast cancer." (PMID 23732710, 2013). "Pak4 overexpression disrupts acinar morphogenesis, and, similarly, human breast cancer cells form highly disorganized structures when grown in 3D culture." (PMID 23732710, 2013). "These high Pak4-expressing human breast cancer cells form highly disorganized three-dimensional (3D) structures in vitro and readily give rise to orthotopic xenograft tumors in nude mice." (PMID 23732710, 2013). "The result is the formation of mammary tumors at a high frequency, indicating that Pak4 can be a driving force in oncogenic transformation of these cells." (PMID 23326684, 2012). "Pak4 is overexpressed in breast cancer cell lines, as well as in primary human breast tumor and rat mammary tumor samples, but it is barely detectable in normal tissue." (PMID 23326684, 2012). "The chromosomal region containing Pak4, 19q13.2, is frequently amplified at a high rate in aggressive breast cancers with basal-like features." (PMID 23326684, 2012). "Breast tumors and breast cancer cell lines frequently have high levels of Pak4, and overexpression of Pak4 in mammary epithelial cells leads to tumorigenesis in mice." (PMID 23326684, 2012). "Tissue samples from breast cancer patients with higher PAK4 levels displayed larger tumors, lymph node metastasis, advanced cancer stages, and poorer survival outcomes, compared to those with lower PAK4 levels." (PMID 39337621, 2024). "Moreover, elevated PAK4 mRNA expression in cancer tissue was strongly correlated with shorter disease-specific survival in breast cancer patients." (PMID 36980457, 2023). "In breast cancer, PAK4 expressed higher in cancer tissue than in normal tissue." (PMID 36980457, 2023). "Besides this, both RUNX1 and LIFR are PAK4 substrates and promote the bone metastasis of ERα-positive breast cancer." (PMID 36230657, 2022). "In breast cancer (BC) cells, PAK4 activates the PI3K/AKT pathway to promote proliferation." (PMID 35800076, 2022). "Here, we provide some experimental evaluation of the combination treatment of ORFV and PAK4 inhibitors and our study could provide a new idea for the development of new treatment strategies for breast cancer." (PMID 35401439, 2022). "PAK4-mediated CEBPB activation upregulates CLDN4 expression to promote cell migration and invasion in breast cancer, thus, PAK4/CEBPB/CLDN4 may be a potential therapeutic target in breast cancer treatment." (PMID 34490085, 2021). "The biological function of nuclear PAK4 in ERα-positive breast cancer osteolytic bone destruction remains unclear." (PMID 32549768, 2020). "In MCF-7 breast cancer cells, PAK4 expression increased migration of the cells on vitronectin, another extracellular matrix protein, and inhibited cell spreading and adhesion to vitronectin by stimulating integrin avβ5 and specifically phosphorylating integrin β544–46." (PMID 33051544, 2020). "Identification of MZF1 as an oncogenic target of PAK4, whose activity is important for invasiveness of ErbB2 positive breast cancer cells, suggests that PAK4 inhibitors might be useful for the treatment of cancers whose aggressiveness depends on MZF1." (PMID 31963147, 2020). "Our results provide that PAK4 could be a novel therapeutic target for ERα-positive breast cancer treatment." (PMID 32549768, 2020).
breast cancer (continued). "Likewise, nuclear PAK4 represses the expression of LIFR to promote the bone metastasis of ER positive breast cancer cells." (PMID 32549768, 2020). "Importantly, we verify changes in RUNX1 subcellular localization when nuclear PAK4 is positive in breast cancer bone metastasis tissues." (PMID 32549768, 2020). "As a kinase, PAK4 plays a biological role mainly by phosphorylating downstream substrates 55, but how PAK4 in ERα-positive breast cancer cells participates in osteolytic bone destruction in a kinase-dependent manner is still unclear and needs further verification." (PMID 32549768, 2020). "Recently, experiments have indicated that PAK4 phosphorylated ERα-Ser305, and PAK4 may be a regulator of tamoxifen resistance by perturbing ERα signaling in breast cancer patients." (PMID 30177834, 2019). "Strikingly, the nuclear accumulation of PAK4 might promote aggressive phenotypes, highlighting nPAK4 as a novel predictive biomarker for ERα-positive breast cancer bone metastasis." (PMID 30177834, 2019). "Importantly, PAK4 protein levels were elevated in PyMT-driven mammary tumors as compared with paired adjacent mammary tissues." (PMID 31399573, 2019). "In addition, PAK4 status is a strong prognostic factor for relapse and poor overall survival in breast cancer patients." (PMID 30177834, 2019). "We also analyzed PAK4 copy number and mutational status in the breast cancer cell lines used throughout the study, but no relevant alterations were found." (PMID 31399573, 2019). "In addition, in contrast to untransformed HMECs, ex vivo bulk tumor cells derived from breast cancer patients (patient-derived cells, PDCs) arrested proliferation upon PAK4–siRNA treatment." (PMID 31399573, 2019). "Importantly, from 6 months of age, PAK4-overexpressing virgin and nulliparous females exhibited lesions that eventually developed into mammary tumors in 25% of the cases." (PMID 31399573, 2019). "Considering also that MMTV–PAK4 overexpression may have facilitated KRAS-driven mammary tumors, and that oncogenic RAS-signaling in untransformed cells activates OIS3, we tested the hypothesis that PAK4 may overcome oncogenic RAS-induced senescence." (PMID 31399573, 2019). "PAK4 is overexpressed in primary human breast cancer and breast cancer cell lines, and the upregulation of PAK4 may be an important event in tumorigenesis that contributes to progression and metastasis." (PMID 30177834, 2019). "Our results reveal a critical function of PAK4 in breast cancer pathogenesis and identify a druggable vulnerability that may be exploited for breast cancer therapy." (PMID 31399573, 2019). "Moreover, breast cancer cells were generated using CRISPR/Cas9 genome editing with single guide RNAs (sgRNAs) targeting PAK4." (PMID 31399573, 2019). "This is consistent with the observation that HER2-positive patients exhibited the highest PAK4 expression among the PAM50 and IC10 breast cancer subtypes and also consistent with the strong correlation observed between PAK4 expression and HER2 signaling in the METABRIC dataset." (PMID 31399573, 2019). "Moreover, hsa-miR199a-3p can also restrain migration and invasion of breast cancer by downregulating PAK4/MEK/ERK signaling pathway." (PMID 31249805, 2019). "In addition, we reported that high PAK4 levels correlate with poor survival of endocrine-treated breast cancer patients." (PMID 31399573, 2019). "Thus, PAK4 is a negative regulator of NF-κB signaling in breast cancer cells, regulating senescence-like growth arrest via the noncanonical NF-κB subunit RELB." (PMID 31399573, 2019). "In addition, we show that the low PAK4/high RELB pattern of expression correlates with better prognosis in HER2-positive breast cancer patients." (PMID 31399573, 2019).
breast cancer (continued). "PAK4 is expressed at low levels in the majority of normal adult tissues and accumulating documents have reported that the aberrant expression of PAK4 is closely related to the diverse cancers, such as glioma, breast cancer, colon and gastric cancers, and prostate cancer." (PMID 28706947, 2017). "In the present study, we investigated whether PAK4 could be used as a biomarker of breast cancer progression and prognosis." (PMID 28407679, 2017). "The Pak4-ERα interaction decreases sensitivity to tamoxifen in MCF-7 human breast cancer cells." (PMID 28978098, 2017). "Additionally, univariate and multivariate analyses identified that PAK4 is the most significant prognostic marker for breast cancer patients in addition to lymph node status." (PMID 28407679, 2017). "The present study supports the functional role of PAK4 in breast cancer, and suggests that PAK4 and PI3K/AKT signaling could serve as a novel target for breast cancer therapy." (PMID 28407679, 2017). "In this study, we sought to identify the role for PAK4 in breast cancer progression." (PMID 28407679, 2017). "PAK4 is barely detectable in normal epithelial tissue, but is frequently activated in breast cancer cell lines as well as in primary human breast cancer specimens and rat mammary tumor samples." (PMID 28407679, 2017). "Numerous studies point to a striking role for PAK4 in breast cancer." (PMID 28407679, 2017). "Additionally, PAK4 gene is located at chromosome 19q13.2, a region frequently amplified in aggressive breast cancers with basal-like features." (PMID 28407679, 2017). "Expression of both PAK4 and P54 in breast cancer was much higher than that in breast fibroma and increased gradually as breast cancer progressed (advanced invasive 32.6 ± 8.2 % > early invasive 12.4 ± 3.5 % > noninvasive 2.0 ± 0.5 % > breast fibroma 0.2 ± 0.1 %; F = 20.325, p < 0.001)." (PMID 27297086, 2016). "It shows that PAK4 may be used as a sensitive indicator and has important significance in judging the malignant degree and pathological types of breast cancer." (PMID 27297086, 2016). "The P54 localization in the cytoplasm and the PAK4 was co-localized, so that PAK4 and P54 proteins may be used as molecular markers for diagnosis and treatment of breast cancer." (PMID 27297086, 2016). "PAK4 and P54 proteins may be used as molecular markers for diagnosis and treatment of breast cancer." (PMID 27297086, 2016). "The expression of both PAK4 and P54 in breast cancer was much higher than that in breast fibroma." (PMID 27297086, 2016). "In breast cancer cells, PAK4 inhibits cell adhesion and promotes cell migration by selectively inducing αvβ5 mediated breast cancer cell motility through the phosphorylation of the integrin β5 cytoplasmic tail and by regulating actin depolymerisation through phosphorylation of LIMK1." (PMID 26554417, 2015). "Nevertheless, our experimental data indicate that PAK4 may be a suitable pharmacological target for the development of therapy to sensitize breast cancer to tamoxifen treatment." (PMID 26554417, 2015). "The clinical correlation between PAK4 and endocrine treated breast cancer patient outcome together with the functional role of PAK4 in tamoxifen response suggest that there may be a regulatory relationship between PAK4 and ERα." (PMID 26554417, 2015). "In contrast, integrin αVβ5 promotes breast cancer cell invasiveness in a PAK4-dependent mechanism." (PMID 26657485, 2015). "In conclusion, PAK4 may be a suitable target for perturbing ERα signaling and tamoxifen resistance in breast cancer patients." (PMID 26554417, 2015). "Our identification of PAK4-mediated phosphorylation of ERα-Ser305 is particularly interesting in the light of the previous correlation between ERα-Ser305-phosphorylation and tamoxifen-resistance in breast cancer patients." (PMID 26554417, 2015).